TNKS (tankyrase)
Diseases named in the same sentence as TNKS in open-access papers (continued):
Sharing a sentence is not in itself a finding about the gene and the disease.
lung adenocarcinoma (7 papers, 2013 to 2024). A carcinoma that arises from the lung and is characterized by the presence of malignant glandular epithelial cells. "E7449, a TNKS small molecule inhibitor, can also reduce TNKS expression in lung adenocarcinoma cells." (PMID 38898581, 2024). "Correlation regression analysis revealed that the high expression of TNKS in 74 cases of lung adenocarcinoma was closely correlated with tumour size (p = 0.000) and tumour‐node‐metastasis (TNM) stage (p = 0.001)." (PMID 38898581, 2024). "Xiaoyan decoction and a small molecule inhibitor both act on TNKS proteins and are new candidates for the treatment of lung adenocarcinoma." (PMID 38898581, 2024). "Our previous study showed that the expression of the TNKS protein was significantly downregulated after Xiaoyan decoction treatment of lung adenocarcinoma cells." (PMID 38898581, 2024). "TNKS overexpression promoted cell growth and proliferation and enhanced the migration and invasion of lung adenocarcinoma cells in vitro." (PMID 38898581, 2024). "We subsequently applied the Xiaoyan decoction and TNKS inhibitors to intervene in lung adenocarcinoma." (PMID 38898581, 2024). "On this basis, the anticancer effect and possible mechanism of action of the TNKS small molecule inhibitor and traditional Chinese medicine Xiaoyan decoction on lung adenocarcinoma cells were evaluated." (PMID 38898581, 2024). "As a first step, we explored the consequences of TNKS/2 blockade on cell motility in four lung adenocarcinoma cell lines—H322, HCC827, H460, and A549—using XAV939 and JNJ-BJ as tool compounds." (PMID 26787475, 2016). "In addition, we found that the expression of TNKS protein was significantly downregulated after Xiaoyan decoction was administered to lung adenocarcinoma cells." (PMID 38898581, 2024). "TNKS is a new target for the treatment of lung adenocarcinoma, the synergistic effects of the TCM compound Xiaoyan decoction and the TNKS inhibitor E7449 in the intervention on TNKS were investigated, and the possible underlying mechanisms involved were clarified." (PMID 38898581, 2024). "Furthermore, the high TNKS expression in 74 lung adenocarcinoma patients was closely related to large tumour size and advanced TNM stage." (PMID 38898581, 2024). "Because recent data have linked Wnt transcriptional signatures to the metastatic competence of lung adenocarcinoma cells, our initial working hypothesis was that the anti-migratory outcome of TNKS/2 inhibition might be ascribed to impaired Wnt signaling." (PMID 26787475, 2016). "Therefore, TNKS can enhance the migration and invasion of lung adenocarcinoma cells in vitro." (PMID 38898581, 2024). "On this basis, we assessed the anticancer effect and possible mechanism of TNKS in lung adenocarcinoma cells by the synergistic use of a TNKS small molecule inhibitor and the TCM Xiaoyan decoction, of which TNKS is a key target, and we discussed the idea of integrating Chinese and Western medicine." (PMID 38898581, 2024). "XAV939 is a small molecule that inhibit Tankyrase inducing β-catenin phosphorylation and non-activation in lung adenocarcinoma A549 cell." (PMID 31256073, 2019). "The qPCR analysis of WIF1 and TNKS expression in three cases of human lung adenocarcinoma revealed the expected repression of WIF1 and moderate overexpression of TNKS2 (as compared to adjacent normal lung tissues) in all examined cases, as well as for TNKS1 in 1 of 3 cases." (PMID 23621985, 2013).
ovarian carcinoma (6 papers, 2017 to 2024). A malignant neoplasm originating from the surface ovarian epithelium. "In this study, we found that TNKS was aberrantly overexpressed in human ovarian cancer tissues and associated with poor patient prognosis." (PMID 30915350, 2019). "Seven SNPs from two genes (TEP1 and TNKS) showed significant associations with ovarian cancer survival (P < 0.05, Q < 0.10)." (PMID 28233473, 2017). "TNKS is a novel and a promising target for cancer treatment and several inhibitors have been investigated in clinical trials of various TNKS-associated human cancers, including ovarian cancer." (PMID 36185280, 2022). "The biological functions of TNKS in cell cycle and apoptosis might contribute to the drug susceptibility of ovarian cancer cells." (PMID 30915350, 2019). "Importantly, in order to investigate the mechanisms underlying the tumorigenic function of TNKS, we found that TNKS inhibition or knockdown suppressed the aerobic glycolysis of ovarian cancer cells by reducing PC through inhibition of Wnt/β-catenin/snail signaling." (PMID 30915350, 2019). "TNKS inhibition or knockdown not only reduced ovarian cancer cell proliferation, colony formation, migration, invasion, and tumorigenic potential in nude mice but also enhanced the drug susceptibility of ovarian cancer cells through arresting cell cycle and inducing apoptosis." (PMID 30915350, 2019). "In this context, TNKS-activated Wnt/β-catenin signaling contributes to colony formation, migration, invasion, and tumorigenic potential of ovarian cancer cell lines, as well as the promotion of aerobic glycolysis, which is often observed in malignant cells." (PMID 32560059, 2020). "In this study, we present for the first the role and mechanism of TNKS in the development of ovarian cancer." (PMID 30915350, 2019). "Next the effect of TNKS knockdown on ovarian cancer cells migration and invasion was evaluated by using wound-healing and transwell assays." (PMID 30915350, 2019). "In order to evaluate the significance of TNKS overexpression, immunohistochemistry (IHC) was used to analyze a series of ovarian cancer samples paraffin-embedded on tissue microarrays." (PMID 30915350, 2019). "Next, data from the colony formation indicated that the ability of ovarian cancer cells to growth in an anchorage-dependent manner was markedly reduced by TNKS inhibition or knockdown." (PMID 30915350, 2019). "Taken together, our findings identified TNKS as an oncogenic regulator of ovarian cancer cells proliferation that promote aerobic glycolysis via activation of Wnt/β-catenin signaling." (PMID 30915350, 2019). "Our results are in concert with a previous study regarding the aberrant overexpression of TNKS in ovarian cancer and its oncogenic activity exhibited through regulating the targets of Wnt/β-catenin signaling." (PMID 30915350, 2019). "TNKS knockdown in ovarian cancer cells inhibited cell proliferation, cell metastatic abilities, and drug susceptibility." (PMID 30915350, 2019). "As a positive regulator of Wnt/β-catenin signaling, both of TNKS mRNA and protein levels were overexpressed in human ovarian cancer tissues, compared with the normal fallopian tube epithelium tissues." (PMID 30915350, 2019). "TNKS inhibition or knockdown reduced ovarian cancer cell proliferation, colony formation, migration, invasion, and tumorigenic potential in nude mice, and these changes correlated with the downregulation of targets (cyclin D1, MDR, and MMP‐9) of Wnt/β‐catenin signalling." (PMID 38898581, 2024). "Given the strong implication of in the molecular pathogenesis of ovarian cancer, we rationalized that TNKS may play important roles in the development of ovarian cancer." (PMID 30915350, 2019). "Together, these results indicate that TNKS overexpression might contribute to drug resistance of ovarian cancer cells through promoting cell cycle progression and antiapoptosis." (PMID 30915350, 2019).
ovarian carcinoma (continued). "Our study demonstrated that TNKS inhibition might give a reliable therapeutic benefit for ovarian cancer." (PMID 30915350, 2019). "Taken together, TNKS could potently facilitate tumorigenesis and metastasis in many respects throughout the progression of ovarian cancer via activation of Wnt/β-catenin signaling." (PMID 30915350, 2019). "In the current study, we found elevated TNKS expression in a subset of human ovarian cancer." (PMID 30915350, 2019). "Hence, these results suggested that promoting metastasis might be one of the oncogenic potentials of TNKS in ovarian cancer." (PMID 30915350, 2019). "Thus, TNKS is required for ovarian cancer cells growth both in vitro and in vivo." (PMID 30915350, 2019). "However, the expression profile of TNKS protein and its roles and mechanisms in ovarian cancer remain unknown." (PMID 30915350, 2019). "When either TNKS or RSPO1 are inhibited, Wnt/β-catenin signaling activity decreases and ovarian cancer cells undergo apoptosis." (PMID 32560059, 2020). "To assess the functional role of TNKS in ovarian cancer cells, we knocked down expression of TNKS in OVCAR-3 cells (high TNKS expression) using TNKS-specific short hairpin RNA lentiviruses (shTNKS)." (PMID 30915350, 2019). "Similarly, we found that PC is required for TNKS to promote glycolysis and snail is critical for TNKS to regulate the expression of PC via Wnt/β-catenin signaling, suggesting PC may become a new target to involve in TNKS-regulated the development of ovarian cancer." (PMID 30915350, 2019). "Additionally, the poly(ADP) ribose polymerase (PARP) Tankyrase (TNKS) activates canonical Wnt signaling in ovarian cancer independent of Wnt ligands through destabilization of the destruction complex." (PMID 32560059, 2020).
cherubism (5 papers, 2013 to 2022). Cherubism is a rare, self-limiting, fibro-osseous, genetic disease of childhood and adolescence characterized by varying degrees of progressive bilateral enlargement of the mandible and/or maxilla, with clinical repercussions in severe cases. "Dysregulation of tankyrase-mediated binding and degradation of protein substrates has been recognized as the pathogenic mechanism of cherubism, a dominantly inherited human disorder." (PMID 30991935, 2019). "ARTD5/6 (formerly Tankyrase 1/2) play a role in Wnt signaling and in controlling the stability of the adaptor 3BP2, mutations of which are mechanistically linked to Cherubism." (PMID 23332125, 2013). "The role of the tankyrase enzyme has been seen in many conditions such as cancer, Wnt/β-catenin signaling, HSV replication, cardiomyocytes, telomeric dysfunction, mitosis, Cherubism, and many other diseases." (PMID 35194449, 2021).
hepatocellular carcinoma (5 papers, 2015 to 2021). A malignant tumor that arises from hepatocytes. "In the present manuscript, we investigated the effect of Tankyrase inhibitors on the growth of hepatocellular carcinoma (HCC) cell lines and the molecular mechanisms involved." (PMID 28877210, 2017). "Altogether, the present data indicate that XAV-939 and G007-LK Tankyrase inhibitors could suppress proliferation of hepatocellular carcinoma cells and downregulate YAP/TAZ by stabilizing AMOTL1 and AMOTL2 proteins, thus representing new potential anticancer drugs against hepatocellular carcinoma." (PMID 28877210, 2017).
prostate carcinoma (5 papers, 2016 to 2024). A carcinoma that arises from epithelial cells of the prostate gland. "USP25 is known to interact with TNKS, influencing prostate cancer cell proliferation via the WNT signaling pathway, which plays a crucial role in PCa progression." (PMID 38321455, 2024). "Tankyrase inhibitors may exert a therapeutic effect in prostate cancer by inhibiting telomerase activity and Wnt signaling, mediated by TRF1 and AXIN stabilization respectively." (PMID 33599076, 2021). "Indeed, inhibition of Wnt/β-catenin signaling by the tankyrase inhibitor XAV939 led to radiosensitization of prostate cancer cells and glioblastoma cells." (PMID 27363012, 2016).
gastric cancer (4 papers, 2016 to 2025). A primary or metastatic malignant neoplasm involving the stomach. "Increased Tankyrase expression correlates with raised telomerase activity and gastric cancer progression; however, a functional connection between telomerase activity and Tankyrase expression remains elusive." (PMID 40904702, 2025). "In the gastric cancer cell line SGC‐7901, Tankyrase inhibitors and telomerase activity inhibitors show a synergistic effect." (PMID 40904702, 2025).
glioma (4 papers, 2017 to 2022). A benign or malignant brain and spinal cord tumor that arises from glial cells (astrocytes, oligodendrocytes, ependymal cells). "Of the eight investigated genes involved in telomere maintenance and telomerase regulation, three (PINX1, TNKS, and TNKS2) were found to be downregulated in all glioma cell lines when compared to individual controls." (PMID 36142793, 2022). "Expression of TNKS and TNKS2 was decreased in glioma cells compared to non-malignant cells and normal brain tissue." (PMID 36142793, 2022).
liver cancer (4 papers, 2017 to 2023). An epithelial or non-epithelial malignant neoplasm that arises from the liver. "For this purpose, appropriate preclinical models such as genetically engineered mouse (GEM) models and patient derived xenograft (PDX) models of liver cancer should be subjected to administration of Tankyrase inhibitors." (PMID 28877210, 2017). "Indeed, inhibitors of TNKS could represent a novel attractive therapeutic target in liver cancers induced by infective microorganisms." (PMID 37512809, 2023). "Subsequent studies have found that TNKS inhibitors such as IWR-1, IWR-2, and JW55 can stabilize AXIN and inhibit the proliferation inhibition mediated by Wnt/β-catenin signaling on many types of tumor cells, including colorectal and liver cancer." (PMID 36185280, 2022).
melanoma (4 papers, 2019 to 2021). A malignant, usually aggressive tumor composed of atypical, neoplastic melanocytes. "The findings warrant a further in-depth preclinical and clinical evaluation of combining checkpoint inhibitors with tankyrase inhibition for the treatment of melanoma." (PMID 32332858, 2020). "In conclusion, YAPhigh is a marker for a melanoma subgroup that includes B16-F10 and tracks with tankyrase inhibitor-induced reduction in MITF expression." (PMID 32332858, 2020). "Further molecular and functional evaluations are required for establishing a precise set of rules for context-dependent treatment efficiency using combined tankyrase and checkpoint inhibitor treatment in human melanoma." (PMID 32332858, 2020). "This study suggests that a combinatorial therapy using tankyrase inhibition can be used to overcome β-catenin-mediated resistance to immune checkpoint blockade in melanoma." (PMID 32332858, 2020). "Our study uncovers a combinatorial therapeutical strategy using tankyrase inhibition to overcome β-catenin-mediated resistance to immune checkpoint blockade in melanoma." (PMID 32332858, 2020). "Finally, upon RNA sequencing of G007-LK-treated human melanoma cell lines and B16-F10 cells, we reveal a transcriptional response profile for a cell line subpopulation displaying high relative baseline YAP signaling activity and predisposition for reduced MITF expression upon tankyrase inhibition." (PMID 32332858, 2020). "Here we show that a specific small-molecule tankyrase inhibitor, G007-LK, decreases WNT/β-catenin and YAP signaling in the syngeneic murine B16-F10 and Clone M-3 melanoma models and sensitizes the tumors to anti-PD-1 immune checkpoint therapy." (PMID 32332858, 2020). "It was suggested that targeting Axin1 stability by post-translational modifications like phosphorylation by GSK-3β, PARsylation by tankyrase-1/2 (TNKS1/2), methylation by protein arginine methyltransferase 1 (PRMT1), and SUMOylation could sensitize melanoma cells to TRAIL-based therapies." (PMID 34577571, 2021). "The RNA sequencing of 18 tankyrase inhibitor-treated human melanoma cell lines and B16-F10 cells shows that tankyrase inhibition context-dependently can influence WNT/β-catenin and YAP signaling, not only in murine B16-F10 cells, but importantly also in a subset of 18 human melanoma cell lines." (PMID 32332858, 2020).
autoimmune disease (3 papers, 2021 to 2024). A disorder resulting from loss of function or tissue destruction of an organ or multiple organs, arising from humoral or cellular immune responses of the individual to their own tissue constituents. "Because the WNT signaling pathway plays a prominent role in autoimmune diseases (fibrosis) and cancer by influencing tankyrase expression, much can be “learned” from it." (PMID 38610846, 2024). "The modulation of tankyrase activity would have therapeutic effects on autoimmune diseases, including SLE." (PMID 33920631, 2021). "The observation that a subset of autoantibodies indicative of systemic autoimmunity arises in female mice lacking tankyrase in myeloid cells suggests that this pathway may play a pathogenic role in the development of human autoimmune diseases in some patients." (PMID 35362478, 2022).
cervical carcinoma (3 papers, 2013 to 2025). A carcinoma arising from either the exocervical squamous epithelium or the endocervical glandular epithelium. "Treatment with XAV939, a tankyrase inhibitor, reduced the survival of cervical cancer cells while increasing radiosensitivity." (PMID 40699862, 2025). "miR-20a promotes migration and invasion by regulating tankyrase, TRF1-interacting ankyrin-related ADP-ribose polymerase 2 (TNKS2) expression in human cervical carcinoma cells." (PMID 23799609, 2013).
colorectal tumor (3 papers, 2019 to 2025). "A novel TNKS inhibitor JW55 directly inhibited the PARP domain of TNKS1/2, leading to increased degradation of β‐catenin to reduce colorectal tumor growth in conditional APC‐mutant mice model." (PMID 41346572, 2025). "Here, we describe here a novel, drug-like small molecule inhibitor of tankyrase MSC2504877 that inhibits the growth of APC mutant colorectal tumour cells." (PMID 30655555, 2019). "In summary, MSC2504877 is a novel, drug-like, tankyrase inhibitor that inhibits APC mutant colorectal tumour cells." (PMID 30655555, 2019).
Hypertension (3 papers, 2022 to 2023). The presence of chronic increased pressure in the systemic arterial system. "Notably, genome-wide association studies indicate that TNKS and TNKS2 (encoding TNKS1 and TNKS2) are associated with MI, ischemic stroke, and hypertension in humans, suggesting a crucial role for TNKSs in the pathogenesis of cardiovascular disease (CVD)." (PMID 36077457, 2022).
osteoarthritis (3 papers, 2015 to 2024). A noninflammatory degenerative joint disease occurring chiefly in older persons, characterized by degeneration of the articular cartilage, hypertrophy of bone at the margins and changes in the synovial membrane. "Thus, although further studies are needed to establish the role of TNKS in osteoarthritis through axin-mediated inhibition of Wnt signaling, it is quite possible that TNKS could be risk factor for osteoarthritis." (PMID 25880085, 2015). "We investigated the effects of a Tankyrase (TNKS-1/2) inhibitor on mechanical stress-induced gene expression in human chondrocytes and examined TNKS-1/2 expression in human osteoarthritis (OA) cartilage." (PMID 38338721, 2024). "Tankyrases (TNKS-1 and TNKS-2) were recently reported as a potential target for disease-modifying osteoarthritis drugs (DMOADs)." (PMID 38338721, 2024).